SOX10 (SRY-box transcription factor 10)
Diseases named in the same sentence as SOX10 in open-access papers (continued):
Sharing a sentence is not in itself a finding about the gene and the disease.
melanoma (continued). "The therapeutic implications of SOX10 loss extend beyond conventional targeted therapies, as SOX10‐deficient melanoma cells exhibit resistance to oncolytic virus immunotherapy—an approach designed to reverse cancer‐associated immune suppression and stimulate antitumor immune responses." (PMID 40458894, 2025). "We show that TEAD targets are highly dependent on TAZ in SOX10-deficient melanoma." (PMID 41193428, 2025). "Melanoma dedifferentiation refers to the tumor's progression toward a less differentiated state, often including the loss of typical melanocytic markers such as S100 protein, SOX10, Melan-A, and HMB-45." (PMID 40125165, 2025). "Notably, we find that p300 KAT activity is essential for the emergence of the invasive phenotype upon SOX10 loss in human melanomas and that A-485 is capable of inhibiting both tumor cell proliferation and invasion in melanoma cells as a single agent." (PMID 38994683, 2024). "As we observed a strong association between MITFhigh expression and EP300/SOX10 co-amplification status, we sought to determine whether this trend was present in a larger set of melanoma cell lines using the CDM." (PMID 38994683, 2024). "Importantly, SOX10 enhances melanocytic development and melanoma cell growth, and SOX10 deficiency is associated with an invasive slow cycling state resulting in acquired resistance to targeted therapies." (PMID 39237877, 2024). "Once melanomas are established, however, this lineage dependency on SOX10 may decrease because the loss of Sox10 activity is associated with drug resistance and a cross-resistance mechanism for both targeted- and immune-based therapies." (PMID 39092608, 2024). "Notably, the loss of only one Sox10 allele is sufficient to counteract the activity of oncogenes, such as Nras and Grm1, and to prevent melanoma in transgenic murine melanoma models." (PMID 39092608, 2024). "Recent reports described the curcumin-induced miR-222-3p upregulation, thus negatively modulating the expression levels of its target SOX10, causing the inactivation of the SOX10/Notch pathway and limiting proliferation, migration, and invasion of melanoma cells." (PMID 38201989, 2024). "Furthermore, SOX10 is implicated in neural and neuroectodermal tumors, such as melanoma, malignant peripheral nerve sheath tumors (MPNSTs), and schwannomas, influencing processes like proliferation, migration, and differentiation." (PMID 38132479, 2023). "We further show that melanoma cells that acquire a drug-resistant state are less susceptible to viral infection, and this cross-resistant state can be recapitulated following the deletion of SOX10." (PMID 38201278, 2023). "Interestingly, targeted therapy resistance can be induced through the loss of SOX10, a key player in melanoma initiation and progression." (PMID 38201278, 2023). "Studies have also shown that the loss of SOX10 increases the cancer stem cell properties of melanoma, which could be the underlying factor in creating this resistant state." (PMID 38201278, 2023). "In addition, S100 protein family, Microphthalmia-associated transcription factor (MITF), SOX10, etc. have been proven to be diagnostic molecular markers for melanoma." (PMID 37427124, 2023). "The data revealed that at the time of progression, the close association of SOX10+ melanoma cells with CD8+ T cells negatively correlated with PFS of melanoma patients and may indicate a potential mechanism for acquired resistance to BRAF/MEK-targeted therapy." (PMID 35058553, 2022). "Indeed, SOX10 positive melanoma cells show an upregulation of genes implicated in pigmentation and cell differentiation while SOX9 positive melanoma cells show an upregulation of genes implicated in EMT." (PMID 35406721, 2022). "However a different study challenged this finding and it has recently been reported that loss of SMARCB1 results in senescence by suppressing SOX10 expression in melanoma cells." (PMID 35323214, 2022).
melanoma (continued). "Importantly, we identify a vulnerability of SOX10-deficient melanoma cells based on the up-regulation of cellular inhibitors of apoptosis-2 (cIAP2)." (PMID 35296667, 2022). "ERK activation, Pten loss, and Tyrp2 expression also were seen in the YUMM1.7 melanoma cell line derived from induced tumors in the Braf Pten mouse model, whereas Sox10 and Tyrp2 were expressed by human A375P cells, representative of primary cutaneous human melanoma cell lines." (PMID 35267510, 2022). "SOX10 loss is associated with melanomas that have acquired resistance to BRAFi16." (PMID 35296667, 2022). "To test our hypothesis, we focused on MITF and SOX10 as the two most essential TFs in skin and used the A375 melanoma cell line harbouring the BRAF activating mutation." (PMID 33073517, 2020). "Indeed, in melanoma, another NC-derived malignancy, SOX10 expression predisposes to tumor development and is associated with a bad prognosis." (PMID 32595833, 2020). "Interestingly, SOX10 expression is required for efficient therapeutic targeting of the activating BRAFV600E mutation in melanoma." (PMID 29315345, 2018). "In addition, SOX10 is highly expressed in melanoma tumors, is rarely mutated in melanoma, and SOX10 knockdown in melanoma cells and tumors causes interrupted cellular proliferation, growth arrest, and reduced tumor size in vivo." (PMID 29315345, 2018). "Moreover, a CD271/Sox10-positive cell in patient biopsies is associated with poor prognosis for melanoma." (PMID 27462428, 2015). "The first study hypothesized that increased EGFR could be the result of an adaptive response of melanoma cells occurring in presence of the drug and due to the activation of TGFβ signaling following loss of the transcription factor SOX10." (PMID 25742786, 2015). "Based on our findings it is conceivable that increased levels of SOX9 might mediate at least some of the anti-tumorigenic effects observed upon SOX10 loss-of-function in melanoma." (PMID 25629959, 2015). "MITF or SOX10 have been extensively investigated and allowed a better comprehension of resistance to cancer therapies, underlying the importance of lineage specific signaling in our understanding of how melanoma still overcomes current treatments in the clinic." (PMID 31118886, 2019). "Thus, the differential expression of SOX10 in melanoma cells and its preference for dimer motifs in those cells could be causative for the formation of melanoma-specific DHS regions." (PMID 26013289, 2015). "Dissection of the right inguinal lymph nodes revealed melanoma metastasis in 10 of 14 lymph nodes, with Immunolohistochemistry showing diffusely positivity for Sox-10 and Melan-A." (PMID 41782886, 2026). "Clear cell sarcoma (CCS) and malignant melanoma share overlapping immunohistochemical profiles, particularly SOX10 and HMB45 positivity, making histopathological differentiation challenging." (PMID 42077576, 2026). "For spindle cell/dedifferentiated melanoma, S100 showed a pooled OR of 161.23 (95% CI 24.55-1058.69), sensitivity of 0.95, and specificity of 0.94 (95% CI 0.85-0.97), while SOX10 yielded a pooled OR of 121.27 (95% CI 6.33-2323.34)." (PMID 42122208, 2026). "Initial histopathological evaluation suggested a spindle cell malignancy; however, immunohistochemical analysis demonstrated positivity for S-100, SOX10, and Melan-A, confirming malignant melanoma." (PMID 42220859, 2026). "In melanoma, SOX10 is crucial for cell proliferation, migration, and cell cycle regulation, with its loss reducing proliferation but increasing invasiveness." (PMID 40458894, 2025). "In BRAF-mutated melanoma cells, the inhibition of ERK1/2 signaling leads to the induction of forkhead box D3 (FOXD3), which influences the sumoylation of SOX10." (PMID 40872623, 2025). "Our multiparameter ploidy sorting approach enabled us to separate melanoma tumor populations based on DNA ploidy (DAPI) and specific melanoma biomarkers (SOX10 and S100)." (PMID 40004220, 2025).
melanoma (continued). "The reported spatial expression of the melanoma signature gene Sox10 shows that Sox10+ cells were significantly reduced after MASKv treatment, further supporting that MASKv can have a therapeutic effect on tumors." (PMID 40303352, 2025). "Collectively, our findings suggest that the oncogenic functions of HK2 in melanoma cells are, at least in part, dependent on the translational regulation of the SOX10 mRNA via its 5′UTR." (PMID 40956859, 2025). "There are also studies confirm that SOX10 hinders immunogenicity of melanoma cells through the IRF4-IRF1 axis." (PMID 40342816, 2025). "On immunohistochemistry, the atypical cells showed diffuse, strong positivity for melanoma markers including SOX10, HMB-45, Melan-A, and S100." (PMID 40236344, 2025). "Modern histopathology routinely includes immunohistochemical stains, such as Sox-10 (Sry-related HMg box gene 10), Melan-A (Melanoma antigen recognised by T cells 1), and PRAME (Preferentially Expressed Antigen in Melanoma)." (PMID 41562710, 2025). "Research indicates that curcumin suppresses melanoma growth and metastasis through the miR-222-3p/SOX10/Notch signaling axis, highlighting its potential as a therapeutic agent against melanoma progression." (PMID 40282947, 2025). "In some of these difficult circumstances, with only SOX10 expression along with weak patchy cytokeratin staining, the only definitive solution remains molecular studies to identify UV/melanoma signature in the tissue sample." (PMID 40025593, 2025). "SOX10 activates the MITF (microphthalmia-associated transcription factor) pathway, which controls genes crucial for melanoma survival and its overexpression is associated with increased tumor aggressiveness and resistance to therapies." (PMID 40647405, 2025). "The authors identified 245 candidate lncRNAs associated with melanoma whose loci are jointly bound by MITF and SOX10, suggesting that DIRC3 exerts broad tumour-suppressive effects through IGFBP5-dependent mechanisms." (PMID 41463281, 2025). "This study shows that it also functions as an RNA-binding protein that regulates mRNA translation, particularly of SOX10, a key factor in melanoma progression, promoting melanoma cell proliferation independently of glycolysis." (PMID 40956859, 2025). "We further showed that HK2-dependent SOX10 mRNA translation is involved in melanoma cell proliferation and colony formation." (PMID 40956859, 2025). "Epigenetic alterations further influence this resistance landscape, with methylation‐mediated repression of both MITF and SOX10 promoting melanoma dedifferentiation and consequent therapy resistance." (PMID 40458894, 2025). "Here, the authors develop two inhibitors of TEAD, capable of resensitising SOX10 knockout melanoma cells to MAPKi and offering a strategy to overcome drug tolerance and improve treatment response." (PMID 41193428, 2025). "One of the few commonalities between MPNSTs and melanomas was the expression of the NC derivative marker Sox10." (PMID 41063628, 2025). "At the protein level, SOX10 was significantly reduced in both melanoma cell lines and in melanocytes." (PMID 41465475, 2025). "Sox10+ melanoma cells had invaded deep into the hypodermis, and nearly all mice contained LN metastases (data not shown)." (PMID 41279375, 2025). "In melanoma, tolerance to MAPK pathway inhibitors is associated with loss of SOX10 and an enhanced TEAD transcriptional program." (PMID 41193428, 2025). "SOX10 emerges as a critical orchestrator of melanoma progression, with its multifaceted functions extending beyond simple growth promotion." (PMID 40458894, 2025). "Melanoma cells were identified based on SOX10 expression, and clustering with UMAP was used to define distinct melanoma cell states." (PMID 41432764, 2025). "Histopathological examination of a transbronchial biopsy demonstrated immunohistochemical positivity for S100 and SOX10, consistent with a diagnosis of melanoma." (PMID 41384184, 2025).
melanoma (continued). "The tumor's AFX-like morphology and partial loss of melanocytic markers (Melan-A negativity with retained SOX10 expression) represent a phenomenon of melanoma dedifferentiation." (PMID 40125165, 2025). "It has been reported that SOX10 reduced the immunogenicity of melanoma cells by activating the IRF4-IRF1 axis." (PMID 40342816, 2025). "As for erasers, FTO can promote anti-PD-1 resistance by modulating m6 A methylation in several vital protumorigenic melanoma cell-intrinsic genes, PD-1, SOX10, and CXCR4." (PMID 40483535, 2025). "Specifically, we assembled a gene regulatory network considering SOX10's role in multipotency, glial cell differentiation, and melanoma plasticity." (PMID 40458894, 2025). "Aberrant expression of these factors contributes to therapy resistance and tumor progression, with SOX10 facilitating the acquisition of a stemness phenotype in melanoma cells." (PMID 40458894, 2025). "Skin biopsy revealed recurrent melanoma, with SOX10 and Melan-A positivity, and imaging showed features concerning for multifocal disease recurrence in the left popliteal fossa." (PMID 41312331, 2025). "This is particularly important since HK2 is an attractive target in cancer and since SOX10 is not only critical in melanoma proliferation but also a factor of resistance to immunologic cell death." (PMID 40956859, 2025). "In particular, a study showed that the downregulation of SOX10 in melanoma activated TGFβ to induce upregulation of EGFR and PDGFRβ, which then conferred resistance to MAPK inhibition." (PMID 40872623, 2025). "These regulators include MAPK signaling pathway indicators p-BRAF and p-ERK, metastatic markers N-Cadherin and Vimentin, proliferative marker PCNA, and melanoma-specific transcription factor SOX10." (PMID 41284701, 2025). "Here, we reviewed and discussed the intricate interplay between SOX10 and miRNAs in melanoma biology including melanogenesis, phenotype switch, and therapy resistance." (PMID 40458894, 2025). "Given our data above showing that sox10 is required specifically in melanocyte patterning and regeneration, we wished to investigate its function in melanoma." (PMID 40879132, 2025). "In melanoma, SOX10 is strongly expressed in primary and metastatic cells, promoting migration and invasion while suppressing melanogenesis and driving senescence." (PMID 41012776, 2025). "A surrogate for melanoma count was chosen; namely, SRY‐related HMG‐box 10 (SOX10) protein‐positive melanoma nuclei, determined by image analysis of WSIs." (PMID 39138753, 2025). "Within melanoma, Gal-1 has a key role in therapy resistance, resisting MAPK inhibitors and chemotherapy, and cancer progression, including promoting immune evasion, SOX10-linked plasticity, and VEGF-independent angiogenesis." (PMID 41918780, 2025). "SOX10 is a melanocytic lineage-specific transcription factor that is highly but heterogeneously expressed in melanoma." (PMID 41193428, 2025). "As a result, the assay established the abundant expression of the melanoma marker gene SOX10 in the superficial melanoma region along with its co‐expression with the proliferation‐associated MKI67 (Figure S6A1)." (PMID 39846232, 2025). "Only 3/96 (3.1%) fish with sox10 knockouts initiated melanomas compared to the 24/94 fish (25.5%) from the NT condition that developed tumors." (PMID 40879132, 2025). "Conversely, exclusion markers like Ber-EP4, CK7, TTF-1, S100, and SOX10 were essential in ruling out basal cell carcinoma, adenocarcinoma, and melanoma." (PMID 40427131, 2025). "Experimental evidence reveals that SOX10 knockdown in melanoma cells triggers profound phenotypic changes, including growth arrest, morphological alterations, and cellular senescence, highlighting its fundamental role in maintaining melanoma cell viability." (PMID 40458894, 2025). "Immunohistochemistry for the melanoma plasticity marker SOX10 showed an inhomogeneous expression in the detected tumor tissue." (PMID 41255880, 2025).
melanoma (continued). "Mechanistically, SOX10 activates both MAPK and PI3K/AKT pathways, which are pivotal for melanoma cell survival and proliferation, while also influencing invasive capacity, as evidenced by reduced cell invasion following SOX10 inhibition." (PMID 40458894, 2025). "In melanoma cell cultures and tumor samples, SOX10/MITF expression was found to correlate with and drive RNF125 transcription." (PMID 40872623, 2025). "This suggests that the distinct melanoma cell states are underpinned by SOX10‐mediated network motifs." (PMID 40458894, 2025). "Advanced imaging (MRI) and immunohistochemical analysis revealed the mass to be a superficial spreading melanoma expressing SOX10, PS100, Melan-A, HMB-45, and PRAME." (PMID 39862670, 2025). "Within the SOX gene family, SOX4, SOX5, SOX9 and SOX10 are established key regulators in melanoma cells establishment and function." (PMID 40866912, 2025). "Immunohistochemical studies demonstrated strong positivity for S100, SOX10, and melanoma cocktail (MART-1/Melan-A, HMB-45, and tyrosinase), with negativity for AE1/AE3, CAM5.2, CK7, and HMB-45." (PMID 40984891, 2025). "Recent studies show that the dysregulation of the transcription factor SOX10 is essential for the development and progression of melanoma." (PMID 40458894, 2025). "One case (Patient 7), despite massive infiltration of CD8+ T and CD20+ B cells within the organoids, SOX10+ melanoma cells were still present." (PMID 41432764, 2025). "Single‐cell studies reveal heterogeneity in MITF and SOX10 expression, correlating with distinct phenotypes in primary melanoma." (PMID 40458894, 2025). "Immunohistochemical markers such as HMB-45, S-100, and SOX-10 play a critical role in distinguishing melanoma from other oral tumors, with spindle and epithelioid cell morphologies frequently observed in histopathological examinations." (PMID 40003600, 2025). "In melanoma, the DepMap has identified SOX10 as the top in vitro genetic dependency necessary for tumor cell proliferation, suggesting it acts as a lineage-specific oncogene." (PMID 40879132, 2025). "The observed upregulation of SOX10, a neural crest transcription factor, in melanoma tissues is in line with its established role in melanocyte specification and maintenance." (PMID 40216818, 2025). "Immunohistochemically, the tumor cells were positive for S100 (5/6), cyclin D1 (2/3), SATB2 (2/3), BCOR (2/4), and TLE1 (1/3) while negative for MUC4 (0/6), keratin (0/5), EMA (0/4), desmin (0/6), CD34 (0/6), SMA (0/5), SOX10 (0/5), and pan melanoma (0/2)." (PMID 40705064, 2025). "Significantly more genes were either up-regulated or down-regulated following TAZ knockdown compared to YAP1 knockdown, indicating that TAZ has a major role in regulating gene expression in SOX10 KO melanoma cells." (PMID 41193428, 2025). "Another interesting example with a pivotal role in melanoma is the transcription factor SOX10, essential for neural crest and oligodendrocyte development." (PMID 40872623, 2025). "SOX10 is well known to promote a more invasive and dedifferentiated melanoma phenotype, in part by sustaining low-MITF, high-motility cell states." (PMID 41465475, 2025). "SOX10 is a key transcription factor in melanocyte biology and melanoma development, and it tends to be homogeneously expressed in most melanomas." (PMID 40647405, 2025). "Conversely, p16 exhibited diffusely present expression, similar to the case of pan melanoma and SOX10, while PRAME revealed a mildly positive reaction." (PMID 41234990, 2025). "In melanoma, the proliferative state is thought to be characterized by high expression of SOX10, whereas the mesenchymal, invasive state is characterized by high expression of SOX9." (PMID 40879132, 2025). "Melanoma cell nuclei were labelled with SRY‐related HMG‐box 10 (SOX10) protein, the sections scanned and StarDist machine‐learning algorithm used to count nuclei in 102 cases of primary cutaneous melanoma." (PMID 39138753, 2025).